KRAS (KRas proto-oncogene, GTPase)
Diseases named in the same sentence as KRAS in open-access papers (continued):
Sharing a sentence is not in itself a finding about the gene and the disease.
colorectal cancer (continued). "In colorectal cancer, mutations of the KRAS and BRAF genes are quite common and can contribute to the activation of cell signaling pathways that lead to cell proliferation and differentiation." (PMID 34063682, 2021). "The definition of R1 is largely concordant to the corresponding level-of-evidence (LOE) in OncoKB (e.g., KRAS exons 2–4 mutations for anti-EGFR antibodies in advanced colorectal cancers)." (PMID 34162978, 2021). "BRAF mutations occur in a minority of colorectal cancers cases (5-15%) compared to KRAS mutations in codon 12 and 13 (40%) and extended KRAS and NRAS mutations (52%)." (PMID 34535182, 2021). "Unfortunately, KRAS G12C mutation is rather uncommon in other solid tumors, namely pancreatic ductal adenocarcinoma and colorectal cancer." (PMID 34064352, 2021). "The mutation of KRAS is found to be higher in colorectal cancer and thought to enhance the malignancy character of the transformed cells." (PMID 33597969, 2021). "KRAS G:T transversions are common in MAP tumors and the success of colorectal cancer treatment options depends on KRAS mutational status." (PMID 33419231, 2021). "We can also mention a cluster of RAS mutated cell lines, usually NRAS mutated for melanomas (e.g., SK-MEL-2) and KRAS for colorectal cancers (e.g., COLO-678), which are classified by the model as resistant." (PMID 33507915, 2021). "Since mutations in KRAS are found in >90% of PDACs and mutated KRAS facilitates changes in sEV cargo content in colorectal cancer, similar functions are however very likely." (PMID 34638330, 2021). "In colorectal cancer, mutation of KRAS (RASMUT) reduces therapeutic options, negatively affecting prognosis of the patients." (PMID 34654798, 2021). "Oncogenic KRAS is one of the genes that is frequently mutated in colorectal cancer, and mutant KRAS is associated with poor prognosis and resistance to therapeutics." (PMID 34822010, 2021). "KRAS mutations are detected in ~ 40% of all colorectal cancers and they are associated with worse prognosis and more aggressive tumor behavior." (PMID 33817986, 2021). "KRAS mutation in colorectal cancer is one of the biological factors of resistance mechanism in EGFR targeted therapy." (PMID 34367944, 2021). "Meta‐analysis of the mutational status of KRAS in CTCs and tumor tissues revealed discrepancies in colorectal cancer patients." (PMID 33448107, 2021). "The predictive value of genomic mutations in colorectal cancer has previously been investigated; the studies concluded that KRAS, as well as RAS, BRAF and PIK3CA mutations, are predictive of tumor response to anti-EGFR therapy." (PMID 34065112, 2021). "In advanced colorectal cancer, KRAS mutations are an independent prognostic factor in treatment with cetuximab and wide-type KRAS is required for panitumumab efficacy." (PMID 33413590, 2021). "We recently demonstrated the power of metabonomics to define the specific profiles of human SW48 colorectal cancer cells carrying different KRAS mutations in codons 12, 13, 61 and 146 compared with their wild-type counterpart." (PMID 34822010, 2021). "Our results demonstrated that LMWF is a potential complementary therapy for enhancing the efficacies of fluoropyrimidine-based chemotherapy in colorectal cancers (CRCs) with the wild-type or mutated KRAS gene through different mechanisms." (PMID 34360807, 2021). "A total of 419 patients with colorectal cancer with initially unresectable liver-limited metastases, who participated in a multicenter prospective trial, were evaluated for tumor tissue KRAS mutation status." (PMID 34820593, 2021). "KRAS was one of the earliest human oncogenes to be described and is one of the most commonly mutated genes in different human cancers, including colorectal cancer." (PMID 34822010, 2021).
colorectal cancer (continued). "From a therapeutic perspective, previous studies focusing on KRAS mutant colorectal cancer and acute myeloid leukemia have indicated that the WT copy of the KRAS gene is associated with resistance to treatment with MEK inhibition." (PMID 34573384, 2021). "SUVmax is also shown to be correlated with KRAS mutation in colorectal cancer, BRAFV600E mutation in thyroid cancer and HER2 expression in gastric cancer." (PMID 33995277, 2021). "Specifically, we compared the metabolic profiles of parental HCT116 KRAS G13D/+ (a cell line isolated from a patient with colorectal cancer in which glycine (G) 13 is mutated to aspartate (D)) and its isogenic derivative cell lines: KRAS+/– and KRAS G13D/–." (PMID 34822010, 2021). "We previously reported that loss of KRAS mutations (“regressive” mutational trajectories) from primary tumors to metastases associated with the oligo-metastatic status in colorectal cancer (CRC)." (PMID 33854968, 2021). "Most colorectal cancers arise through the chromosomal instability pathway due to the accumulation of somatic mutations in protooncogene (KRAS) and tumor suppressor genes such asAPCandTP53." (PMID 32892548, 2021). "In our cohort, only 4 patients had colorectal cancer with KRAS/NRAS mutations, three of them (all B2M-wt) received ICB therapy and showed PR as best response." (PMID 34168989, 2021). "KRAS mutations are common in lung adenoma, pancreatic ductal cancer and colorectal cancer whilst NRAS mutations are found in melanoma." (PMID 33367512, 2021). "KRAS is an oncogene involved in colorectal cancer pathogenesis, and it is mutated in about one-third of colorectal cancers." (PMID 34884270, 2021). "Data from published full exome sequences of colorectal cancer have suggested that GNAS mutations are quite often accompanied by mutations in KRAS and/or BRAF." (PMID 35141142, 2021). "An oncogenic alteration in KRAS gene is the most frequent in pancreatic cancer, colorectal cancer and lung cancer, while mutated HRAS is the most common in dermatological, head and neck cancers." (PMID 33549031, 2021). "In an in vitro colorectal cancer study, phosphotyrosine proteomic profiles comparison between the two most frequent KRAS mutations, KRASG12D and KRASG13D, has been performed." (PMID 33777798, 2021). "Characteristics of studies analyzed the association of SUVmax with KRAS and Ki-67 in colorectal cancer." (PMID 34956868, 2021). "KRAS mutation also affects intraluminal vesiculation of several miRNAs such as the oncogenic miR-10b in colorectal cancer cells." (PMID 34203713, 2021). "KRAS mutation G12C is present in about 13% of lung cancer, 3% of colorectal cancer, and in a smaller percentage of other epithelial tumors." (PMID 33777798, 2021). "Since NF1 is frequently co-mutated in KRAS G13-mutated colorectal cancer, these tumor cells can respond to EGFR inhibitors in an NF1-dependent manner." (PMID 34680229, 2021). "The results of this study conclusively underline that the roles of the PIK3CA and KRAS mutational status as potential predictive markers for adjuvant therapy with aspirin in patients with colorectal cancer require prospective studies." (PMID 34638442, 2021). "Pancreatic cancer, which has the highest mortality rate of any solid tumour, has an approximately 90% KRAS mutation rate, while colorectal cancer has a rate close to 50%." (PMID 34200676, 2021). "KRAS mutations are observed in 15–25% of all cancers, whither 30–40% of colorectal cancer harbor at least a single mutation on that gene." (PMID 33916923, 2021). "Specific mutations in the KRAS gene are closely related to the precise treatment of colorectal cancer." (PMID 34335949, 2021).
colorectal cancer (continued). "The results indicated that KRAS expression was significantly lower in tumour tissue than in tissue obtained from normal subjects, providing evidence that KRAS gene mutation is an independent risk factor for the prognosis of colorectal cancer patients." (PMID 34490250, 2021). "In this study, we analyzed a cohort of six colorectal cancer patients harboring KRAS mutations and with wild-type BRAF from a transcriptional perspective, with the aim of elucidating the role of the stromal cells in tumor progression." (PMID 34439343, 2021). "The KRAS mutation is one of the leading driver mutations in colorectal cancer (CRC), and it is usually associated with poor prognosis and drug resistance." (PMID 34299137, 2021). "Aberrant activation of the Wnt/β-catenin pathway due to APC (adenomatous polyposis coli) loss and Kirsten ras (KRAS) mutation is highly associated with malignant evolution, e.g., metastasis, of colorectal cancer (CRC)." (PMID 33917100, 2021). "In a KRAS/BRAF mutated colorectal cancer cell model, a reversible oxidation of GAPDH was observed after vitamin C treatment." (PMID 33804775, 2021). "A total of 118 patients with MSS/L colorectal cancer, including 54 patients with KRAS mutations and 64 KRAS wild type patients, were included in this study." (PMID 33995628, 2021). "Relationships between the role of KRAS mutation and prognosis have been reported in various carcinomas such as colorectal cancer and pancreatic cancer." (PMID 34797780, 2021). "Other researchers reported similar results, showing that the dual inhibition of KRAS and p38 inhibited tumor growth in KRAS-mutated colorectal cancer cells and KRAS-mutated LUAD cells." (PMID 34885068, 2021). "The mutual exclusivity of EGFR amplification and KRAS mutations has been described in lung adenocarcinoma and colorectal carcinoma (CRC) and co-expression caused cytotoxic effect on cells." (PMID 34285259, 2021). "In a mouse model of colorectal carcinoma (CRC) bearing mutated KRAS a major structural change of the gut microbiota was identified as the link between HFD and inflammation." (PMID 34298645, 2021). "In this retrospective study were included 22 patients with 65 liver metastases due to colorectal cancer, and the patients were divided into two groups with KRAS mutation positive (+) (n: 10, 30 lesions) and the wild-type group (n: 12, 35 lesions)." (PMID 32858990, 2020). "While 30%–40% of colorectal cancers carry a KRAS mutation, a higher mutation frequency is found in females compared to males, with pronounced differences for tumors in the proximal colon." (PMID 33330090, 2020). "The clinical data of patients with colorectal cancer from January 2014 to December 2018 were retrospectively collected, and the associations between KRAS mutations and other indicators were analysed." (PMID 33183271, 2020). "In our recent publication, we have explored at the molecular level the consequences of reovirus administration to patients with KRAS mutated colorectal cancer (CRC)." (PMID 33426543, 2020). "In the present study, we investigated the in-vitro anti-cancer potential of six diarylpentanoids against a panel of BRAF- and KRAS-mutated colorectal cancer cell lines including T84, SW620, LoVo, HT29, NCI-H508, RKO, and LS411N cells." (PMID 32858795, 2020). "Point mutations in the KRAS gene are present in approximately 35–45% of colorectal cancers, and serve as a negative predictive factor of response to anti-EGFR therapy." (PMID 32300895, 2020). "Previous controversial reports have evaluated intertumoral heterogeneity, showing both discordance and concordance in the KRAS mutation status between the primary tumor and the matched metastases in patients with colorectal cancer." (PMID 33002027, 2020). "In the present study, we examined the anti-tumor activities of a novel anti-EGFR monoclonal antibody, EMab-17 (mouse IgG2a, kappa), in colorectal cancer (CRC) cells with the KRAS p.G13D mutation." (PMID 32839411, 2020).
colorectal cancer (continued). "An illustrative example of bi-strand SLAM-MS of a DNA sample from colorectal cancer with the KRAS GGC13GAC mutation shows a high resolution of wild-type and mutant melt peaks upon examination of both strands." (PMID 32214156, 2020). "KRAS mutation occurs in cancers such as pancreatic cancer, cholangiocarcinoma, colorectal cancer, and lung cancer." (PMID 32111094, 2020). "Specific cancer genes can also have sex-biased patterns of somatic mutation, including the lower frequency of KRAS mutation among males with colorectal cancer, higher mutation frequency of PBRM1 and KDM5C in males and BAP1 in females with renal carcinoma." (PMID 33330090, 2020). "Identifying the mutation status of KRAS is important for optimizing treatment in patients with colorectal cancer (CRC)." (PMID 33183271, 2020). "One of the most common events in colorectal cancers is a mutation ofthe KRASgene.KRAS,a member of theRASgene family, is one of the most studied oncogenes present in the short arm of chromosome 12." (PMID 32939513, 2020). "The detection of Kirsten rat sarcoma viral oncogene homolog (KRAS) gene mutations in colorectal cancer (CRC) is key to the optimal design of individualized therapeutic strategies." (PMID 32487083, 2020). "Testing for RAS mutation became a routine molecular pathology activity in colorectal cancer leading to several studies on KRAS clonality and primary/metastasis comparisons." (PMID 32725342, 2020). "Prognostic effect of KRAS mutation and side of tumor in colorectal cancer is a highly controversial subject." (PMID 32079384, 2020). "In other cancers, such as pancreatic cancer and colorectal cancer, KRAS mutations are also frequent." (PMID 32117436, 2020). "Based on the TCGA data in cBioPortal, the most frequent KRAS mutations in pancreatic cancer are G12D, G12V, and G12R; the most frequent KRAS mutations in colorectal cancer are G12D, G12V, and G13D." (PMID 32117436, 2020). "Previous studies reported that approximately 10–11% of advanced colorectal cancers showed intratumoral heterogeneity of KRAS or BRAF mutations where mutations were identified in only one of the multiple formalin‐fixed, paraffin‐embedded tumor blocks." (PMID 32449983, 2020). "For example, KRAS point mutations are causally linked with acquired resistance to cetuximab treatment in colorectal cancer." (PMID 32698317, 2020). "For example, the presence of a KRAS mutation has long been recognized as a marker of resistance to EGFR inhibitors (EGFRi) for patients with colorectal cancer (CRC)." (PMID 33153459, 2020). "Our data is in concordance with a meta-analysis from Cheng-Bo Han and colleagues who analyzed the KRAS mutation status between primary and metastatic tumor samples in patients with colorectal cancers." (PMID 33002027, 2020). "It has been known that 20-30% human cancers, including a high percentage of pancreatic, lung, and colorectal cancers, are driven by mutations in KRAS." (PMID 33122197, 2020). "Next, we investigated the impact of MCM7 knockdown in other colorectal cancer cell lines harboring KRAS or BRAF mutations." (PMID 32612138, 2020). "The aim of this study is to systematically summarize the accuracy of KRAS mutation measurement in colorectal cancer using cell-free DNA in liquid biopsy samples, with tumor tissue sample as reference (gold standard)." (PMID 32590745, 2020). "Two of the three cancer patients carrying the KRAS gene mutations suffered from colorectal cancer surgery and adjuvant chemotherapy, and another case is lung cancer without chemotherapy." (PMID 32207862, 2020). "To examine the possible interaction with RAS signaling, we investigated the mutation frequency and their mutual exclusivity with KRAS mutations in human colorectal cancer using the mutation profile of TCGA database." (PMID 33060766, 2020). "The total survival rate of colorectal cancer patients harboring KRAS mutations was significantly lower than that of the patients without KRAS mutations." (PMID 32207862, 2020).
colorectal cancer (continued). "KRAS mutations are prevalent in 40–45% of patients with colorectal cancer (CRC) and targeting this gene has remained elusive." (PMID 32552875, 2020). "Cologuard (indicated for colorectal cancer screening) is a kit that includes a molecular analysis for DNA mutations (such as KRAS mutation), methylation biomarkers such as BMP3 and NDRG4 methylation, and an immunochemical assay for human hemoglobin." (PMID 33114412, 2020). "The significance of KRAS mutations has been demonstrated in a genetic colorectal cancer model, in which mutant KRAS harboring adenomatous polyposis coli (APC) mutations induced tumorigenesis and metastasis." (PMID 32974155, 2020). "We utilized the genetically engineered organoids to model colorectal cancer (CRC) with an oncogenic KRAS mutation as a model system for HTS and uHTS platform development." (PMID 32678871, 2020). "For instance, the KRAS(G12V) mutation stimulates metastasis in colorectal cancer models in a manner much stronger than the KRAS(G13D) mutation." (PMID 33003386, 2020). "KRAS mutations have been reported to enhance homologous recombination repair in preference to NHEJ in colorectal cancer cells." (PMID 33195430, 2020). "Here we demonstrate that the suppression of MCM7 is synthetic lethal in KRAS mutated colorectal cancer cells, which specifically rely on high MCM7 levels." (PMID 32612138, 2020). "In this study, we propose a protocol for a systematic review and meta-analysis on the accuracy of KRAS mutation detection in colorectal cancer using liquid biopsy sample, with paired tissue sample as control." (PMID 32590745, 2020). "It is equally interesting that in KRAS mutant colorectal cancers, simultaneous mutations of RYR2, MUC15, and FAT3 are frequent." (PMID 32725342, 2020). "Anti-EGFR antibody therapy for unresectable colon cancer was found to be ineffective in cases with RAS (KRAS/NRAS) gene mutations (about 40% of colorectal cancers), and RAS genetic testing was established as a companion diagnostic tool." (PMID 33383632, 2020). "On the same lines, recent data showed a synergistic effect between fasting-mimicking diet and vitamin C in KRAS mutated colorectal cancer." (PMID 33115525, 2020). "Currently, KRAS mutations are hot-spot driver mutations and the most frequent KRAS mutant is KRAS G12D that is expressed in ∼45% of pancreatic adenocarcinomas and ∼13% of colorectal cancers." (PMID 32850843, 2020). "KRAS mutation occurs in 30 to 50% of colorectal cancers (CRCs) and has been suggested to be associated with proliferation and decreased apoptosis." (PMID 32128213, 2020). "Mutations in TMPRSS13 have been previously identified in colorectal adenomas, and their regional presentation in our study (lesion-common mutations) indicates that TMPRSS13 mutations in colorectal cancers can be early events like APC or KRAS mutations." (PMID 32023847, 2020). "Nearly 45% of colorectal cancer (CRC) patients harbor a mutation in their KRAS gene for which, despite many years of research, there are still no targeted therapies available." (PMID 32731506, 2020). "KRAS mutations occur in colorectal cancer and are often predictive of poor sensitivity to cetuximab or panitumumab." (PMID 32793499, 2020). "Collectively, our data indicate that the combination of a fasting-mimicking diet and vitamin C represents a promising low toxicity intervention to be tested in randomized clinical trials against colorectal cancer and possibly other KRAS mutated tumors." (PMID 32393788, 2020). "In patients with primary colorectal cancer, we detected KRAS mutation in the tissue in 54% of cases, in liver metastases of these patients it was 47.8% of cases." (PMID 32867151, 2020). "The KRAS G12D mutation is a well-studied oncogenic driver leading to the development of aggressive lung and colorectal cancers." (PMID 32463822, 2020).